CDC73 (cell division cycle 73)
Diseases named in the same sentence as CDC73 in open-access papers (continued):
Sharing a sentence is not in itself a finding about the gene and the disease.
parathyroid carcinoma (continued). "A deeper analysis of gene expression and functional prediction suggested that Wilms tumor 1 (WT1) is a potential biomarker for CDC73-mutant parathyroid carcinoma, which was further validated through immunohistochemistry." (PMID 37121965, 2023). "For example, CDC73 is a tumor suppressor, which can prevent cells from growing and dividing too fast or uncontrolled, and is closely related to parathyroid carcinoma." (PMID 35111402, 2022). "It was observed that about 18% of the parathyroid carcinomas showed specific methylation of the CDC73 gene." (PMID 35628190, 2022). "Genetic variants associated with parathyroid cancer and familial PHPT have been reported, and MEN1, CDC73, and RET mutations are known to be associated with the pathogenesis of parathyroid cancer or familial PHPT." (PMID 35586626, 2022). "Patients with familial PHPT or parathyroid cancer had germline mutation in MEN1, CASR, and CDC73, classified as pathogenic or likely pathogenic variants." (PMID 35586626, 2022). "Several germline mutations in CDC73, MEN1, CASR, and PTH are associated with benign sporadic PHPT or parathyroid cancer." (PMID 35586626, 2022). "Apart from mutations, LOH encompassing the CDC73 gene locus and aberrant CDC73 promoter methylation have also been reported as somatic events in parathyroid carcinoma." (PMID 33269427, 2021). "The inactivation of CDC73, and its gene product parafibromin, is a major driver of parathyroid cancer." (PMID 33778063, 2021). "Mutations in human CDC73 (also called HRPT2) identified in cases of sporadic and hereditary parathyroid carcinomas appear to primarily be loss-of-function mutations including frameshifts, premature stop codons, and deletions that result in truncated proteins." (PMID 29320491, 2018). "Mutations in CDC73 have been frequently detected in patients with HPT-JT and also occur in 20–29 % of individuals with apparently sporadic parathyroid carcinoma." (PMID 27658992, 2016). "CDC73 mutations frequently underlie the hyperparathyroidism-jaw tumor syndrome, familial isolated hyperparathyroidism (FIHP), and parathyroid carcinoma." (PMID 24823466, 2014). "Parathyroid carcinoma constitutes < 1% of cases of primary hyperparathyroidism and it is usually associated with HPRT2 (CDC73) mutation (tumor suppressor gene)." (PMID 25276444, 2014). "Long-term and more closely follow-up is required in patients of parathyroid carcinoma for high rates of recurrence and distal metastasis, especially in HRPT2/CDC73 mutation carriers." (PMID 23029104, 2012). "Dysfunction of parafibromin, encoded by the HRPT2/CDC73 gene, is thought to be a major player in the development of malignant parathyroid tumors." (PMID 23029479, 2012). "In our previous study, we suggested that WT1 may be a potential marker for CDC73-mutant parathyroid cancer." (PMID 40434298, 2025). "As HPT-JT patients carry germline CDC73 gene mutations or deletions, it comes as no surprise that the prevalence of parathyroid carcinoma in this patient category is much higher (15–30%) than in unselected PHPT patient cohorts (< 1%)." (PMID 33269427, 2021). "Moreover, as the majority of HPT-JT kindred develop adenomas, other genetic aberrations apart from the inactivation of CDC73 are likely to be required to propel the invasive behavior in parathyroid carcinomas." (PMID 33269427, 2021). "Thus, deletion of CDC73 exons 1–10 resulted in parathyroid carcinoma diagnosed at the ages of 18 and 32 years in two male family members (members III-3 and II-5, respectively), whereas other members have parathyroid adenomas or atypical adenomas." (PMID 24823466, 2014). "The most severe PHPT and phenotypes were encountered in two males with the exon 1–10 deletion of CDC73, and both of these had parathyroid carcinoma, at ages 32 and 18 years; they also had headaches and severe hypertension as the initial manifestations of PHPT, which resolved after primary surgery." (PMID 24823466, 2014).
parathyroid carcinoma (continued). "A germline inactivating mutation of the CDC73 tumor suppressor gene (formerly known as HRPT2 gene; OMIM#607393) can be identified in most patients with HPT-JT and in approximately 20% of patients with sporadic parathyroid carcinoma." (PMID 25177504, 2014). "Inactivating the CDC73 tumor suppressor gene (previously HRPT2) increases the susceptibility of heterozygous carriers to a range of conditions, including hyperparathyroidism-jaw (HPT-JT) syndrome, familial isolated hyperparathyroidism (FIHP), and parathyroid carcinoma (PC)." (PMID 37807045, 2023). "In particular, parathyroid cancers harboring CDC73 inactivating mutations, a frequent genetic aberration occurring in about 70% of parathyroid cancers, showed a reduced proportion of YAP1 nuclear positive cells, while they were lost in samples harboring the CDC73 wild type allele." (PMID 33670622, 2021). "CDC73 genetic and clinical testing should be considered for the following: patients with a suspicion or diagnosis of parathyroid carcinoma; family members of patients with a diagnosis of parathyroid carcinoma; and patients with a positive family history of parathyroid tumor of any sort." (PMID 28774260, 2017). "Accordingly, all patients with newly diagnosed parathyroid carcinoma should have a meticulous review of family history and should be considered for CDC73 mutation screening whether or not other features of HPT-JT are present." (PMID 25177504, 2014). "Biallelic inactivation in CDC73 has been detected in tumors in HPT-JT kindred and in sporadic parathyroid carcinomas and renal carcinomas." (PMID 27658992, 2016). "A previously unreported intragenic deletion of exons 1 to 10 of CDC73 was detected in a three-generation family with FIHP, due to adenomas, atypical adenomas, and parathyroid carcinomas." (PMID 24823466, 2014). "By contrast, parathyroid carcinomas (PCas) showed a remarkable loss of YAP1 nuclear staining irrespective of the cell division cycle 73 (CDC73) or MEN1 status." (PMID 33670622, 2021). "For family members of patients with parathyroid carcinoma periodic biochemical screen regardless of CDC73 status is recommended." (PMID 28774260, 2017). "The findings of the present study underline the need for performing CDC73 deletion analysis in HPT-JT, FIHP, parathyroid carcinoma, and/or severe early-onset PHPT patients who do not have point mutations." (PMID 24823466, 2014). "CDC73, also called parafibromin, is another marker: many parathyroid carcinomas are negative." (PMID 34659402, 2021). "Unlike CDC73, other germline disorders that predispose to parathyroid adenomas, such as those involving mutations in MEN1, FHH, CASR, CGM2, are rarely, if ever, associated with parathyroid carcinoma." (PMID 31661917, 2019). "Thus, it is recommended that deletion analysis of the CDC73 gene should be performed in HPT-JT, FIHP, parathyroid carcinoma, or severe early-onset PHPT patients who do not have CDC73 point mutations (15, –, 17)." (PMID 24823466, 2014).
hyperparathyroidism (48 papers, 2008 to 2025). Hyperfunction of the parathyroid glands resulting in the overproduction of parathyroid hormone. "Cell division cycle 73 (CDC73; previously hyperparathyroidism type 2 (HRPT2)) is located on chromosome 1q31.2 and encodes a 531 protein, parafibromin; it was initially discovered in 26 affected kindreds with hyperparathyroidism-jaw tumor syndrome (HPT-JT)." (PMID 38038882, 2024). "Whole exome sequencing in the index case revealed a novel 99-bp heterozygous insertion, likely pathogenic variant in the exon 2 of CDC73 gene causing hyperparathyroidism jaw tumor syndrome." (PMID 37909004, 2023). "Inactivating mutations in CDC73, a tumor suppressor gene, have been reported in cases of ossifying fibroma in the setting of hyperparathyroidism-jaw tumor syndrome and occasionally in sporadic cases of ossifying fibroma." (PMID 37232789, 2023). "Hyperparathyroidism-jaw tumour syndrome is caused by germline inactivating variants of the CDC73 (also called HRPT2) tumour suppressor gene." (PMID 37810884, 2023). "As the name of syndrome “hyperparathyroidism-jaw tumour syndrome” indicates, carriers of germline mutation in CDC73/HRPT2 gene have increased risk to develop hyperparathyroidism and ossifying fibromas of the maxillary and mandibular bones." (PMID 35805976, 2022). "Our results support the benign nature of this CDC73 variant, as individuals with both alterations presented a prevalence of hyperparathyroidism of 50% (3/6), similar to the 55% (6/11) of family members with only the MEN1 mutation." (PMID 34889280, 2021). "This region contains the CDC73 gene which has been associated with hyperparathyroidism-jaw tumor syndrome, features of which include recurrent, functional parathyroid adenomas and behavioral issues." (PMID 29739732, 2019). "The CDC73 gene is a tumour suppressor gene, mutations in which have been associated with hyperparathyroidism–jaw tumour syndrome and familial hyperparathyroidism." (PMID 30547231, 2019). "Germline mutations in CDC73 are associated with hyperparathyroidism-jaw tumour syndrome, a very rare disorder that has been associated with Wilms tumour and, on one occasion, papillary RCC." (PMID 29680948, 2018). "Screening for the mutated CDC73 confirmed carrier status in the proband’s daughter and the biochemistry and ultrasonography led to pre-emptive surgery and resolution of the hyperparathyroidism." (PMID 28774260, 2017). "Here we describe a rare case of HPT-JT syndrome, in which the hyperparathyroidism in affected family members co-segregated with an altered CDC73 allele harboring a large intragenic deletion and a 5’UTR variant." (PMID 28774260, 2017). "Germ-line inactivation mutations of the tumor suppressor gene - HRPT2/CDC73 are related to hyperparathyroidism-jaw tumor syndrome (HPT-JT, OMIM 145001), in which about 90% of cases presenting PHPT and up to 15% of cases presenting PC." (PMID 23029104, 2012). "Two patients had a history of hereditary hyperparathyroidism, including a CDC73 germline mutation in one patient and an unknown cause in the other." (PMID 36010997, 2022). "We studied the prevalence and phenotype of family members who manifested both genetic alterations (MEN1 and CDC73); individuals with both alterations presented with a prevalence of hyperparathyroidism of 50% (3/6) compared to 55% (6/11) with MEN1 mutation alone." (PMID 34889280, 2021). "The Hyperparathyroidism with Jaw-Tumours syndrome is caused by mutations of the CDC73 gene: it has been suggested that early onset of the disease and high Ca2+ levels may predict the presence of a CDC73 mutation." (PMID 29755684, 2018). "While MEN1, MEN4, and hyperparathyroidism-jaw tumor syndrome involve inactivating pathogenic variants of tumor suppressor genes MEN1, CDKN1B, and CDC73, respectively, MEN2 is caused by activating mutations of RET proto-oncogene." (PMID 40277809, 2025).
hyperparathyroidism (continued). "A recent study demonstrated that CDC73 involve in ubiquitin-proteasome degradation in hyperparathyroidism-jaw tumor syndrome." (PMID 41318472, 2025). "Hyperparathyroidism occasionally develops secondary to genetic disorders, though CDC73-related diseases such as hyperparathyroid jaw tumor syndrome (HPT-JT) are among the least common." (PMID 37654924, 2023). "A minority of COsFs are linked to inactivating mutations in the tumor suppressor gene CDC73 (HRPT2), especially in those cases that are part of hyperparathyroidism–jaw tumor syndrome." (PMID 36378285, 2022). "It is noteworthy that in one family with hyperparathyroidism-jaw tumor syndrome (HPT-JT), the c.-4_-11insG 5’UTR variant was found to be in cis with a deletion of exons 4 to 10 of CDC73." (PMID 34889280, 2021). "Several responsible genetic germline changes associated with parathyroid tumors in familial syndromes, such as MEN1 in MEN 1, RET in MEN 2 A, and CDC73/HRPT2 in HPT-JS (hyperparathyroidism-jaw tumor syndrome), have been identified." (PMID 30104706, 2018). "Nevertheless, since CDC73 genetic screening was not conducted for this patient, the possibility of CDC73-associated hyperparathyroidism cannot be excluded." (PMID 41312166, 2025). "Hyperparathyroidism-jaw tumour syndrome is one such autosomal dominant familial disorder, characterised by a mutation in the cell division cycle 73 (CDC73; also known as HRPT-2) tumour suppressor gene." (PMID 34104498, 2021). "In 70% of sporadic PC cases, as well as in 15–20%, associated to hyperparathyroidism with jaw tumour syndrome (HPT-JT), pathogenic variants of the CDC73 gene were found, with the corresponding loss of expression of the encoded parafibromin protein, on the tumour tissues." (PMID 32411220, 2020). "To date, reports have shown that more than 10% of patients with hyperparathyroidism may have a germline mutation involving the MEN1, RET, cell division cycle 73 (CDC73), calcium-sensing receptor (CASR), cyclin-dependent kinase inhibitor (CDNK1B), or PTH genes." (PMID 29983117, 2018). "Furthermore, parafibromin/Cdc73 is a tumor suppressor encoded by HRPT2, a gene that is mutated in hyperparathyroidism-jaw tumor syndrome." (PMID 22408743, 2011). "Hyperparathyroidism-jaw tumor syndrome (HPT-JT or HRPT2) and Familial isolated primary hyperparathyroidism (FIHP, HRPT1) are autosomal dominant disorders derived by a germline alteration of the cell division cycle 73 (CDC73) gene (1q31.2)." (PMID 38281202, 2024).
parathyroid tumors (37 papers, 2008 to 2025). "A loss of nuclear parafibromin staining in HJT-associated parathyroid tumours is caused by pathogenic CDC73 variants." (PMID 38396977, 2024). "Germline DNA analysis for HRPT2/CDC73 mutation is advised in all patients with parathyroid neoplasm for the possible advantage for first-degree families." (PMID 36532647, 2022). "Biallelic mutation in CDC73 is strongly related to the malignancy of parathyroid tumors, among which parathyroid cancer (PC) is a rare cancer with an unfavorable prognosis." (PMID 36211470, 2022). "Tumor suppressor gene mutations such as MEN1 and CDC73 were demonstrated to be involved in tumor development in both familiar and sporadic types; however, the epigenetic features of the parathyroid tumors are still a little-explored subject." (PMID 35628190, 2022). "Compared with the malignant lesions with a high risk of recurrence, atypical parathyroid tumors with parafibromin deficiency have a low risk of recurrence and subsequent CDC73 gene sequencing is necessary for this entity." (PMID 36415001, 2022). "CDC73-mutated parathyroid tumors are characterized by loss of H2BK120ub1, a histone modification that normally opens the chromatin structure permitting gene transcription and has a role in histone cross-talking and histone H3 methylation (H3K4me and H3K79me)." (PMID 34681865, 2021). "Somatic, intragenic, and inactivating alterations of CDC73 are the most common variant in parathyroid tumors." (PMID 33778063, 2021). "Herein, numerous CDC73 alterations were detected in (34/134; 25%) parathyroid tumors; of these, 51% were nonsense mutations, 29% INDELs, and 20% missense mutations, and these results were consistent with those reported previously." (PMID 33778063, 2021). "Previously, CDC73 mutations have been reported to be associated with tumors of the parathyroids, kidneys, uterus, and exocrine pancreas." (PMID 33150274, 2020). "Parathyroid tumours in the Cdc73+/− (n=25, age >17 months), when compared to similarly aged wild-type Cdc73+/+ littermates (n=20), were associated with increased mean (±s.e.m)." (PMID 28288139, 2017). "For these purposes, we studied nine parathyroid tumors with established CDC73 gene mutations by a-CGH, SNP microarray, CDC73 copy number analysis and CDC73 promoter bisulfite Pyrosequencing." (PMID 23029479, 2012). "Most common recurrent copy number alterations detected by a-CGH in CDC73-mutated parathyroid tumors (T2–T8) with corresponding region of LOH." (PMID 23029479, 2012). "While studies have demonstrated a distinct global gene expression profile of CDC73 mutated parathyroid tumors compared to CDC73 wild-type tumors, very little is known about the molecular cytogenetic profile." (PMID 23029479, 2012). "Germline mutations leading to loss of heterozygosity in the tumour suppressor genes MEN1 (menin) and CDC73 (formerly HRPT2) combined with a second mutation in somatic cells can increase the predisposition to parathyroid tumours." (PMID 21747852, 2011). "Furthermore, loss of nuclear CDC73 in primary parathyroid tumours as the result of CDC73 mutation led to significant depletion of H2Bub1, suggesting that CDC73 functions as a key protein associating the PAF1C with the ligase machinery that synthesises H2Bub1." (PMID 33233707, 2020). "In addition to parathyroid tumors, this deletion was associated in two males with thoracic aortic aneurysms, which possibly represents a new manifestation of CDC73 mutations." (PMID 24823466, 2014). "While it is known that CDC73-mutated parathyroid tumors display specific gene expression changes compared to CDC73 wild-type cases, the molecular cytogenetic profile in CDC73-mutated cases compared to unselected adenomas (with an expected very low frequency of CDC73 mutations) remains unknown." (PMID 23029479, 2012).